RNU6-1105P (RNA, U6 small nuclear 1105, pseudogene)
Gene: Small nuclear RNA gene on chromosome 3 (186,771,841 to 186,771,947, reverse strand). Ensembl gene ENSG00000207505.
Homologues: Orthologues: chimpanzee U6 (98% identical), macaque U6 (87% identical). Paralogues in human: RNU6-25P (85% identical), RNU6-38P (85% identical), RNU6-574P (85% identical), RNU6-1 (84% identical), RNU6-1011P (84% identical), RNU6-1158P (84% identical), RNU6-128P (84% identical), RNU6-15P (84% identical), RNU6-2 (84% identical), RNU6-207P (84% identical), RNU6-21P (84% identical), RNU6-27P (84% identical), and 1288 more.